GNG5 (G protein subunit gamma 5)
Diseases named in the same sentence as GNG5 in open-access papers (continued):
Sharing a sentence is not in itself a finding about the gene and the disease.
glioma (continued). "The positive clustering results of this study might be attributed to some characteristics of glioma tissue, such as the glioma-specific 1p19q co-deletion that affected the expression of GNB1, GNG5, GNG7, GNGN8, and GNG12." (PMID 34222011, 2021). "Further, we used TIMER to analyze the relationship between GNG5 expression and infiltration abundance of six immune cells (B cells, CD4+ T cells, CD8+ T cells, neutrophils, macrophages, and dendritic cells) after purity correction in glioma." (PMID 34098960, 2021). "To further reveal the expression of GNG5 in gliomas, we analyzed the expression level of GNG5 in glioma and normal brain tissues based on transcriptome data in TCGA database and chip data in GSE131273 dataset, respectively." (PMID 34098960, 2021). "GNG5, which is part of the G-protein family, has been associated with different malignant tumors, though the role of GNG5 in glioma has not been studied." (PMID 34098960, 2021). "Glioma patients with high GNG5 expression had shorter overall survival (OS; P < .0001) and disease‐free survival (DFS; P < .0001) compared with the low GNG5 group using the GEPIA2." (PMID 33000557, 2020). "However, the role of GNG5 in contributing to the pathological mechanism in glioma has not been reported." (PMID 34098960, 2021). "Using the same antibody HPA004102 from the IHC-based HPA database, protein expression level of GNG5 protein increased in the order of normal brain tissue, LGG and HGG among different patients, which further confirmed the important role of TNFRSF1A in gliomas at the protein level." (PMID 32257943, 2020). "However, the potential value of GNG5 in gliomas is not entirely clear." (PMID 33000557, 2020).
lung carcinoma (3 papers, 2021 to 2025). "Additionally, GNG5 has been linked to apoptosis in human chondrocytes and lung cancer cells." (PMID 40433374, 2025). "M1-Exos inhibit the proliferation, invasion, and metastasis of lung cancer cells through miRNA-let-7b-5p and GNG5 signaling pathways and inhibit the anti-apoptotic ability of lung cancer cells." (PMID 36643646, 2023). "Based on the impact of GNG5 on lung cancer, we developed an in-depth understanding of the mechanism of Exos on lung cancer invasion and metastasis." (PMID 36643646, 2023). "Additionally, genes coexpressed with GNG5, such as AK2, are highly expressed in lung cancer and can lead to poor prognosis in patients; besides, RER1 as a coexpressed gene with GNG5, could promote the progression of pancreatic cancer and reduce the survival rate of patients." (PMID 34098960, 2021).
Alzheimer disease (2 papers, 2024). A progressive, neurodegenerative disease characterized by loss of function and death of nerve cells in several areas of the brain leading to loss of cognitive function such as memory and language. "The down-regulated DEGs in NM versus NN were primarily focused on ribosome (about 26 DEGs, including RPL37A and RPL35), Alzheimer’s disease (about 20 DEGs, including SNCA and COX8A), and retrograde endocannabinoid signaling (about 6 DEGs, such as NDUFA1 and GNG5)." (PMID 38660519, 2024).
astrocytoma (2 papers, 2020 to 2021). "Subsequently, GNG5 expression was up‐regulated in histology order of normal brain, oligodendroglioma, astrocytoma and GBM." (PMID 33000557, 2020).
breast carcinoma (2 papers, 2019 to 2025). "These include NCOA7-TPD52L1 in breast cancer, GNG5-NMI in colon cancer and FRAS-MRPL1 in lung squamous cell carcinoma." (PMID 40672284, 2025). "Network analysis on the cancer genome atlas (TCGA) breast cancer dataset revealed interaction between CXCL12 and CXCR7 (ACKR3), and a number of G-protein family members (GNG5, GNB4, GNB2, GNG12, GNG7, GNGT1, and GNAI3)." (PMID 30993013, 2019).
endometrial cancer (2 papers, 2020 to 2021). Primary or metastatic malignant neoplasm involving the endometrium (mucous membrane that lines the endometrial cavity). "Previous studies have suggested that GNG5 shows elevated expression in endometrial cancer and in infiltrating ductal carcinoma of the breast." (PMID 34098960, 2021).
glioblastoma (2 papers, 2021 to 2025). The most malignant astrocytic tumor (WHO grade IV). "Similarly, in glioblastoma YY1 was found to promote glycolysis and tumor progression through transcriptional activation of G protein subunit Gamma 5 (GNG5)." (PMID 41327312, 2025).
infiltrating ductal carcinoma of the (2 papers, 2021). "GNG5 has been shown to play an important role in various cancers such as endometrial carcinoma where it is highly expressed, and in invasive ductal carcinoma of the breast where it regulates the secretion of E-cadherin through the Wnt signaling pathway." (PMID 34098960, 2021).
Acidosis (1 paper, 2018). Abnormal acid accumulation or depletion of base. "Acidosis can also cause a well-characterized stimulation of renal GNG5." (PMID 29391429, 2018).
Anxiety (1 paper, 2024). Intense feelings of nervousness, tension, or panic often arise in response to interpersonal stresses. "GNG5@EVRVG-injected 5×FAD and FAD4T mice showed higher anxiety-like behavior relative to their respective control groups, and siGNG5 partially rescued anxiety-like behavior in 5×FAD and FAD4T mice." (PMID 39528445, 2024).
craniopharyngioma (1 paper, 2021). A benign, partly cystic, epithelial tumor of the sellar region, presumably derived from Rathke pouch epithelium. "Furthermore, POP4, a GNG5 coexpressing promoter gene, is highly expressed in prostate cancer cells, while RIMS1, a GNG5 coexpressing suppressor gene, is lowly expressed in craniopharyngioma." (PMID 34098960, 2021).
gastric cancer (1 paper, 2025). A primary or metastatic malignant neoplasm involving the stomach. "Among the 19 uniquely identified genes, 7 (GSPT1, TFF3, KLF4, ITK, GNB2L1, FLI1, and GNG5) were not included in the KEGG gastric cancer pathway, indicating that they have not been previously recognized as canonical GAC-related genes." (PMID 41284725, 2025).
invasive breast carcinoma (1 paper, 2020). A carcinoma that infiltrates the breast parenchyma. "In addition, it has been revealed that GNG5 involved in PI3K-AKT and Wnt signaling pathway, and associated with reduced E-cadherin expression in invasive breast cancer." (PMID 32431729, 2020).
tumor (10 papers, 2018 to 2025). "One possible mechanism underlying this effect is that M1-EVs can transport miR-let-7b-5p to tumor cells, where miR-let-7b-5p regulates the GNG5 protein level, leading to increased expression of the pro-apoptotic protein Bax and promoting tumor cell apoptosis." (PMID 40485727, 2025). "Investigations have shown that exosomes can transfer miR-let-7b-5p to lung tumor cells, inhibiting tumor cell proliferation and promoting tumor cell apoptosis by regulating GNG5 protein levels." (PMID 38983267, 2024). "miR-let-7b-5p from macrophage M1 is transported to lung cancer cells through exosomes, regulates GNG5 protein level to inhibit tumor cell proliferation and promote tumor cell apoptosis." (PMID 38523627, 2024). "Exosomes can transport miR-let-7b-5p to tumor cells, and miR-let-7b-5p can inhibit tumor cell proliferation and promote tumor cell apoptosis by regulating the GNG5 protein level." (PMID 36643646, 2023). "GNG5, a subunit of G-protein, has been reported to promote the proliferation and migration of tumor cells." (PMID 34098960, 2021). "This study explored the applicability of M1 macrophage exosomes (M1-Exos) as gene carriers and the effects on GNG5 protein, and further examined whether macrophage repolarization could inhibit tumor activity." (PMID 36643646, 2023). "Next, we explored whether there is a correlation between GNG5 expression and the tumor immune microenvironment." (PMID 34098960, 2021). "In vivo experiments further confirmed that the growth tendency of tumor tissue could be obviously inhibited by downregulated GNG5." (PMID 34098960, 2021). "In addition, we also found that the migration ability of tumor cells was reduced after the reduction of GNG5 expression and was significantly different from that of the control group (i P < 0.001)." (PMID 34098960, 2021). "Furthermore, we analyzed the correlation between the expression of GNG5 and infiltration level of tumor-infiltrating immune cells using TIMER." (PMID 34098960, 2021). "G protein subunit gamma 5 (GNG5), a subunit of G-protein, promoting the proliferation and migration of tumor cells, was also related to the immune activity." (PMID 40034328, 2025). "Consistent with the RNA-seq data, the protein expression levels of FCGRT, and GNG5 were upregulated in tumor tissues when compared with the normal controls." (PMID 32431729, 2020).
cancer (5 papers, 2019 to 2024). A tumor composed of atypical neoplastic, often pleomorphic cells that invade other tissues. "Transcriptional expression of GNG5 was found to be significantly associated with BLCA individual cancer stages, BLCA molecular subtypes and OS." (PMID 35503998, 2022). "We found that high expression of GNG5 promotes the activation of a series of cancer-related signaling pathways." (PMID 34098960, 2021). "For instance, M1 macrophages release exosomes containing miRNA-let-7b-5p, which regulate the G protein subunit gamma 5 (GNG5) signaling pathway, suppressing cancer cell proliferation and inhibiting their anti-apoptotic ability." (PMID 38655063, 2024). "The association of mRNA expression of predicted target genes (PDCD6, GNG5, PHF6, MAL2, SLC25A15, PTDSS1) with clinicopathological parameters of BLCA patients were analyzed by UALCAN, containing BLCA individual cancer stages and molecular subtypes." (PMID 35503998, 2022). "Multivariate analysis indicated that transcriptional expression of predicted target genes (PDCD6, GNG5, PHF6, MAL2, SLC25A15 and PTDSS1) were significantly correlated with BLCA individual cancer stages and molecular subtypes." (PMID 35503998, 2022). "In this study, KEGG analyses results of the blue module showed that GNG5 was involved in PI3K/Akt signalling pathway and pathways in cancer." (PMID 33000557, 2020). "Furthermore, we performed a pan-cancer analysis of predicted target genes (PDCD6, GNG5, PHF6, MAL2, SLC25A15 and PTDSS1) by using TIMER." (PMID 35503998, 2022). "Additionally, high transcriptional expression of PDCD6, GNG5, PHF6, MAL2, SLC25A15 and PTDSS1 were significantly correlated with BLCA individual cancer stages and molecular subtypes." (PMID 35503998, 2022).
GNG5 also shares sentences with these, for which no sentence is quoted: colon cancer (2 papers); neuroblastoma (2); acute myeloid leukemia (1); adenocarcinoma (1); anaplastic astrocytoma (1); anaplastic oligodendroglioma (1); atherosclerosis (1); chronic myeloid leukemia (1); CNS tumours (1); cognitive deficits (1); colitis (1); head and neck squamous cell carcinoma (1); hematologic disorder (1); ischemia (1); low grade glioma (1); lung (1); lung adenocarcinoma (1); lung squamous cell carcinoma (1); oligodendroglioma (1); osteosarcoma (1); ovarian serous cystadenocarcinoma (1); pancreatic adenocarcinoma (1); pancreatic cancer (1); prostate carcinoma (1); sarcoma (1); skin cutaneous melanoma (1); uterine carcinosarcoma (1); van Maldergem syndrome (1).